POLB (DNA polymerase beta)
Diseases named in the same sentence as POLB in open-access papers (continued):
Sharing a sentence is not in itself a finding about the gene and the disease.
cancer (26 papers, 2013 to 2025). A tumor composed of atypical neoplastic, often pleomorphic cells that invade other tissues. "Previous studies have shown a correlation between single nucleotide polymorphisms (SNPs) of the POLB gene and the risk to develop various cancers." (PMID 41568291, 2025). "On the other hand, POLB variants with low catalytic activity are also linked to an increased risk of cellular transformation and cancer susceptibility." (PMID 38245510, 2024). "In previous studies, the gene mutation and protein expression of POLB were associated with tumor metastasis in several cancer types." (PMID 33673690, 2021). "In different cancer cell lines and cancer patients, the expression of POLB is associated with tumorigenesis." (PMID 33673690, 2021). "In line with this, the Sweasy group has identified and characterized various functional POLB variants that have been implicated in the development of cancer." (PMID 32547565, 2020). "There is evidence that some of the POLB polymorphisms found in cancer cells correlate with defects in the repair of DNA damage induced by several anti-cancer agents." (PMID 26090616, 2015). "The second scenario is based on the genetic liability of POLB in HR deficient cancer cells." (PMID 41568291, 2025). "Therefore, the genetic vulnerability of cancer cells that harbor POLB polymorphism at dRP lyase domain or somatic mutation likely cause the perturbs the BER pathway and sensitizes cancer cells to PARP1 inhibitors." (PMID 41568291, 2025). "Such a translocation of CALR and its dissociation from POLB exhibit some degree of heterogeneity that is linked to cell type and initiating trigger, resulting in varying expression and functions of Calr in different types of normal and cancer settings." (PMID 38245510, 2024). "Although R137 is a key amino acid site for proper POLB function in maintaining genomic DNA stability and physiological homeostasis, the causal relationship between the POLB R137Q mutant and cancer development remains unknown." (PMID 38245510, 2024). "It was reported that POLB variants can be detected in up to 30% of human cancers." (PMID 32547565, 2020). "Additionally, POLB could be a potential target for cancer cells that are deficient MMR and BRCA1/2 to promotes synthetic lethality." (PMID 41568291, 2025). "The first scenario describes the impact of POLB dysregulation and MMR deficiency on cancer cells survival." (PMID 41568291, 2025). "Dysregulation of POLB is likely a potential genetic liability for cancer cells to enhance sensitivity for treatment." (PMID 41568291, 2025). "LUP inhibits lyase activity of DNA polymerase beta and protect cancer tissues against the damaged-DNA agents." (PMID 40341998, 2025). "Since both POLB-driven BER process and circadian clock are extensively involved in cancer development, we next evaluated the impacts of POLB on HCC progression from a chronobiological view." (PMID 38245510, 2024). "Our results suggest that POLB plays a significant role in modulating inflammatory signaling, and they provide a mechanistic basis for future potential cancer immunotherapies." (PMID 36624848, 2022). "We found that the POLB expression in cancer cells from OSCC patients was lower than that in normal oral epithelial cells." (PMID 33673690, 2021). "DNA polymerase-β (POLB) is an important enzyme in base excision repair and contributes to gene instability, leading to tumorigenesis and cancer metastasis." (PMID 33673690, 2021). "There is also promise in BER proteins that are more downstream in the pathway, for example, inhibition of DNA polymerase beta POLB inhibition has been shown to sensitize cancer cells to the oxaliplatin, cisplatin, and the DNA methylating compound temozolomide." (PMID 25988138, 2015).
cancer (continued). "Furthermore, defect in POLB promotes genetic liability of the cancer cells for different targeted and synthetic lethality-based treatment strategies." (PMID 41568291, 2025). "If the DNA repair function mediated by POLB is overly active, it may reduce the retention of damage induced by chemotherapeutic drugs, making cancer cells more resistant to subsequent treatment and thus increasing the risk of chemoresistance." (PMID 41427247, 2025). "Overexpression of DNA polymerase beta mRNA has been correlated with a number of cancer types." (PMID 31416422, 2019). "In addition, our study shows that POLB polymorphism perturbs the BER pathway and sensitizes cancer cells to PARP1 inhibitors." (PMID 26090616, 2015). "Such POLB variants may result in BER deficiencies and increase the risk of cancer development." (PMID 38245510, 2024). "The most frequently amplified genes across the Pan-Cancer Atlas were NBN (n = 4,275, 40.8%), EXO1 (n = 3,714, 35.4%), PARP1 (n = 3,695, 35.2%), PRKDC (n = 3,650, 34.8%) and POLB (n = 2,794, 26.6%)." (PMID 32226530, 2020). "In addition, we find that the drug target of idarubicin (TOP2A) and Cytarabine (POLB) form a significant protein-protein interaction network (P < 1.0 × 10−16), indicating that the predictive biomarkers work as the direct interactive proteins of cancer drug targets." (PMID 33362849, 2020). "Notwithstanding, it is well known that gene repair is one of the most relevant mechanisms of resistance to anti-cancer drugs and two proteins related to DNA repair, PRIM1 and POLB, were detected in both EV subpopulations (CTB and AV) in NR patients." (PMID 31014274, 2019). "The most frequently amplified genes across the pan-cancer atlas were BRIP1 (HDR, 8.04%), POLB (BER, 6.54%), MUS81 (HDR, 6.42%), NBN (HDR, 6.31%), and EXO1 (MMR, 6.26%), while the most frequently deleted genes were BRCA2 (HDR, 6.44%), XRCC2 (HDR, 6.38%), and CUL5 (NER, 6,28%)." (PMID 36081518, 2022). "In this study, we aimed to investigated whether POLB interferes with the cell cycle and genomic integrity of OSCC and then modulates the cancer cell growth." (PMID 33673690, 2021). "However, in this study, POLB had a positive and protective impact on OSCC patients, which is different from the finding of previous studies of other cancer types." (PMID 33673690, 2021). "However, TYMS, DUT, POLB, LIG1 and FEN1 have been identified by others as PARGi synthetic lethality genes, and these observations support the notion that inhibition of nucleotide biosynthesis and BER can sensitize cancer cells to pharmacological PARG inhibition." (PMID 39015544, 2024).
infection (9 papers, 2011 to 2025). The state of being infected such as from the introduction of a foreign agent such as serum, vaccine, antigenic substance or organism. "The expression of APMV polB peaked at 3 hours post-infection (hpi), while the expression of APMV mcp peaked at 6 hpi and was maintained until 9 hpi." (PMID 40071923, 2025). "At 12 hpi, polB expression increased again, and mcp expression decreased, suggesting that the first infection cycle ends and secondary infection starts at this point." (PMID 40071923, 2025). "Because MpoV-45T and MpoV-46T cannot be discriminated by flow cytometry, we performed qPCR targeting the viral DNA polymerase gene B (polB) to examine the infection dynamics of each virus in the dual infection experiments." (PMID 39173010, 2024). "Our studies provide evidence for differential and ecologically relevant consequences of infection by the most closely related prasinoviruses, with 98.0% PolB nucleotide identity, known to infect the prominent marine picophytoplankton species O. lucimarinus." (PMID 30924271, 2019). "Concerning in vitro evaluations, polB alone reduced in vitro amastigote infection of macrophages (10 μg/mL) without complete parasite elimination, even at higher concentrations." (PMID 31042710, 2019). "Among them, several genes encoding for enzymes involved in DNA metabolism were induced upon infection, such as DNA polymerases POLK and POLB, DNA helicase RECQL, and DNA glycosylase SMUG1 involved in various types of DNA repair, including mismatch repair, base excision repair, and direct repair." (PMID 24812617, 2014). "Since the infection cycle of Sputnik was not fully explored, we first determined the time points for RNA sequencing based on the expression timing of marker genes: the DNA polymerase B (polB) gene of APMV and the major capsid protein (mcp) genes of both APMV and Sputnik." (PMID 40071923, 2025). "We detected a strong association of NEIL2 with full length SARS-CoV-2 5’-UTR RNA, mimicking the in vivo post infection CoV-2 RNA-NEIL2 interactions, but not with the 5’-UTR RNA of several host genes; GAPDH, HPRT and DNA polymerase β (POLB) as controls." (PMID 38071370, 2023).
tumor (6 papers, 2019 to 2025). "We analyzed a tissue array from 133 OSCC patients and discovered that low POLB expression was associated with advanced tumor stage and poor overall survival." (PMID 33673690, 2021). "Our work shows that H. pylori infection in BER deficient mice decrease tumor latency and increase tumor incidence suggesting that POLB is required to suppress H. pylori induced carcinogenesis." (PMID 31216714, 2019). "Existing studies have revealed the dual roles of POLB in tumors: on the one hand, research has confirmed that overexpression of POLB can directly promote tumor progression, which means that its high expression may be associated with increased tumor malignancy and poor survival prognosis." (PMID 41427247, 2025). "For example, POLB was found to be overexpressed in approximately one-third of a diverse range of matched tumor samples." (PMID 38245510, 2024). "Consistently, we found that genetic mutation of POLB (reduced enzymatic activity) reduced the liver tumorigenesis, and in vitro studies further confirmed the anti-tumor properties of POLB dysfunction." (PMID 38245510, 2024). "POLB expression is correlated with early tumor stage and better survival, and it is an independent biomarker for predicting favorable prognosis in OSCC." (PMID 33673690, 2021). "In tumor cells, POLB might additionally contribute to the preservation of the tumor cell genome integrity." (PMID 38245510, 2024). "Indeed, the transcriptome data from the liver of normal and tumor-baring mice were clustered, and the circadian rhythm was identified as the most responsive pathway to POLB signals." (PMID 38245510, 2024). "Moreover, a subcutaneous xenograft tumor model established by POLB KO HepG2 cells exhibited reduced tumor volumes and weights." (PMID 38245510, 2024). "We firstly compared the basal expression of POLB in normal oral epithelial cells and tumor part." (PMID 33673690, 2021). "There was a positive correlation between the levels of POLB expression and tumor stage." (PMID 33673690, 2021). "Therefore, it can be speculated that POLB may not only affect patient survival prognosis by directly promoting tumor progression but also participate in tumor treatment response by regulating DNA repair efficiency." (PMID 41427247, 2025). "Hence, even at ZT13, the peak time of POLB expression, it is conceivable that POLB may contribute to the stabilization of the genome induced by mutagens, thereby promoting tumor development." (PMID 38245510, 2024). "It should be noted that if the POLB was not mutated, the POLB’s preservation of genomic integrity may remain consistent in either normal cells or tumor cells." (PMID 38245510, 2024). "Consequently, POLB within the cells may have already recognized and adapted to the mutant genome of the tumor, regarding it as the correct genomic sequence." (PMID 38245510, 2024). "In addition, PER1, as one of the critical genes involved in tumor cell resistance to apoptosis, may also partially receive and amplify oncogenic signals from POLB." (PMID 38245510, 2024). "More importantly, POLB dysfunction with R137Q mutant significantly alleviated the HCC progression, and its anti-tumor effects were more profound at ZT13, indicating the circadian clock is potentially involved in relaying the oncogenic signal of POLB." (PMID 38245510, 2024).
neurodegenerative disease (1 paper, 2023). A disorder of the central nervous system characterized by gradual and progressive loss of neural tissue and neurologic function. "Accordingly, mutations in the POLB gene can influence Polβ functioning and can lead to cancers, neurodegenerative diseases, or premature aging." (PMID 36982964, 2023).
stomach (1 paper, 2019). "This work suggests that the induction of iNOS in POLB mutant mice during H. pylori infection may play an important immunological role to induce stomach carcinogenesis." (PMID 31216714, 2019).
POLB also shares sentences with these, for which no sentence is quoted: anemia (1 paper); dermatitis (1); hepatocellular carcinoma (1); melanoma (1); nephritis (1); oral squamous cell carcinoma (1); Parkinson disease (1); Sepsis (1); viral infections (1); Werner syndrome (1).